EEF2K (eukaryotic elongation factor 2 kinase)
Diseases named in the same sentence as EEF2K in open-access papers (continued):
Sharing a sentence is not in itself a finding about the gene and the disease.
melanoma (19 papers, 2019 to 2025). A malignant, usually aggressive tumor composed of atypical, neoplastic melanocytes. "Overall, these findings suggested that EEF2K deficiency impairs melanoma cell migration, invasion and metastasis." (PMID 35184394, 2022). "In this study, we demonstrated that eEF2K is positively associated with PD-L1 level, and that inhibition of eEF2K downregulates PD-L1 expression in melanoma." (PMID 35347072, 2022). "Mice injected with EEF2K deficient melanoma cells showed a decrease in metastatic burden, with fewer lung micro‐metastases per lung section, as detected using H&E staining of the tumour nodule specimens." (PMID 35184394, 2022). "To uncover the underlying target of EEF2K in the regulation of melanoma cell proliferation and metastasis, we performed RNA sequencing in EEF2K knockdown and control SK‐MEL‐28 cells." (PMID 35184394, 2022). "In this study, we used a cohort of 38 patients with melanoma who received anti-PD-1 treatment to explore the association between eEF2K expression and immunotherapy efficacy against melanoma." (PMID 35347072, 2022). "Moreover, Ki67 IHC staining and TUNEL assay for the excised tumours indicated a significant increase in cell proliferation and decrease in apoptosis when SPP1 was overexpressed in EEF2K‐deficient melanoma cells." (PMID 35184394, 2022). "Together, these in vivo results support that eEF2K deficiency enhances the therapeutic efficacy of PD-1 mAb therapy, and may provide an effective combination therapeutic strategy for treatment of melanoma." (PMID 35347072, 2022). "Eukaryotic elongation factor-2 kinase (eEF2K) plays a critical role in melanoma cells, affecting both protein translation and cholesterol metabolism, particularly by regulating the translation of mRNA for SREBP-2, a key factor in cholesterol biosynthesis." (PMID 38921444, 2024). "In DOX-treated human melanoma cells, eukaryotic elongation factor-2 kinase (eEF-2K) directs the cross-talk between pyroptosis and autophagy." (PMID 36831326, 2023). "Pyroptosis that doxorubicin induces in melanoma cells goes through the eucharyotic elongation factor 2 kinase (eEF-2K) /GSDME pathway." (PMID 37705746, 2023). "Taken together, these results supported the notion that SPP1 contributes to EEF2K‐mediated melanoma progression." (PMID 35184394, 2022). "In conclusion, our study demonstrated that EEF2K plays an oncogenic role in melanoma progression via the p‐STAT3/SPP1 axis." (PMID 35184394, 2022). "To investigate the pro‐oncogenic role of EEF2K in melanoma, we overexpressed EEF2K in melanoma cells and confirmed that EEF2K overexpression promotes melanoma cell proliferation in vitro and in vivo." (PMID 35184394, 2022). "Consistent with the results of previous studies, we found that EEF2K silencing promoted melanoma cell apoptosis and cell cycle arrest at G0/G1 phase." (PMID 35184394, 2022). "The expression of EEF2K was found to be important for melanoma cell proliferation, by regulating the production of proteins important in the uptake of cholesterol, compared to other translated proteins." (PMID 35408842, 2022). "To further explore the biological functions of EEF2K in melanoma, we performed EEF2K silencing in four melanoma cell lines using shRNA, and cell proliferation was significantly suppressed as detected using the CCK‐8 assay." (PMID 35184394, 2022). "After silencing STAT3 with siRNA, as indicated by a decrease in STAT3 and p‐STAT3, SPP1 was significantly decreased even in EEF2K‐overexpressing melanoma cells." (PMID 35184394, 2022). "EEF2K silencing markedly attenuated the malignant phenotypes of melanoma cells, including proliferation, migration, invasion and metastasis." (PMID 35184394, 2022). "In this study, we found that higher eEF2K expression correlates with a better therapeutic outcome and a prolonged survival in patients with melanoma treated with anti-PD-1 immunotherapy." (PMID 35347072, 2022).
melanoma (continued). "Collectively, our results revealed that EEF2K silencing suppresses melanoma cell proliferation and tumour growth, and overexpression of EEF2K increases cell proliferation and tumour growth." (PMID 35184394, 2022). "High eEF2K expression is correlated with better therapeutic response and longer survival in patients with melanoma treated with PD-1 monoclonal antibody (mAb)." (PMID 35347072, 2022). "We found that EEF2K silencing caused significant tumour growth and volume delay in xenografted melanoma tumours, but the bodyweight was comparable between the control and EEF2K silencing groups." (PMID 35184394, 2022). "Knockdown of EEF2K in melanoma cells reduced the levels of cholesterol and the protein levels of LDL-R (crucial for cholesterol uptake), HMGCR (rate limiting enzyme for cholesterol synthesis), and SREBP2 (transcriptional regulator of both pathways)." (PMID 35408842, 2022). "Results indicated that melanoma‐related pathways were significantly enriched in the high EEF2K group (p < .001)." (PMID 35184394, 2022). "To investigate the role of EEF2K in melanoma, we first checked its expression using tissue array and found that EEF2K was overexpressed in melanoma." (PMID 35184394, 2022). "In particular, p-GSK3β/S9 level was positively correlated with eEF2K and PD-L1 levels in these melanoma samples, which were consistent with our in vitro and in vivo studies." (PMID 35347072, 2022). "We next investigated the role and clinical value of eEF2K in patients with melanoma treated with anti-PD-1 therapy." (PMID 35347072, 2022). "Now, we have validated that EEF2K silencing inhibits melanoma progression by repressing the STAT3‐SPP1 axis." (PMID 35184394, 2022). "The function of eukaryotic elongation factor‐2 kinase (EEF2K) in melanoma were investigated in vitro and in vivo." (PMID 35184394, 2022). "As a calcium/calmodulin‐dependent protein kinase, EEF2K is widely expressed in most tumours but moderately expressed in melanoma." (PMID 35184394, 2022). "Since cholesterol metabolism is considered to be an important pathway involved in melanoma development, the effect of inhibiting EEF2K on cholesterol levels in cultured cells was examined." (PMID 35408842, 2022). "Taken together, these results suggested that EEF2K promotes melanoma progression through the STAT3/SPP1 pathway." (PMID 35184394, 2022). "Next, levels of EEF2K were knocked down in melanoma cell lines using four different siRNAs and effects on cellular proliferation examined by assessing metabolism using the MTS assay." (PMID 35408842, 2022). "Silencing of eEF2K by two different siRNAs significantly decreased PD-L1 expression in three human melanoma cell lines, and this effect was also shown in the murine melanoma cell line B16F10." (PMID 35347072, 2022). "Suppression of elongation factor-2 kinase (eEF-2K) leads to autophagy inhibition and pyroptosis enlargement to reinforce the antitumor efficacy of doxorubicin to melanoma cells." (PMID 32093389, 2020). "In a recent study, the results revealed that eEF-2K also played an important role in pyroptosis of human melanoma cells induced by doxorubicin." (PMID 31616642, 2019). "Additionally, doxorubicin has been shown to induce pyroptosis in melanoma by inhibiting eukaryotic elongation factor-2 kinase (eEF-2K), which not only enhances the anti-tumor effects but also suppresses autophagy." (PMID 39949740, 2025). "In addition, recent in vivo experiments in mice revealed that eukaryotic elongation factor 2 kinase (eEF2K) promotes immunosuppression of melanoma via PD-L1 stabilization mediated by GSK3β inactivation." (PMID 37554324, 2023). "Moreover, the sensitivity of Doxorubicin to melanoma cells was increased after silencing eEF-2K resulting in Doxorubicin-induced autophagy switching to GSDME-dependent pyroptotic cell death." (PMID 36071875, 2022). "Delayed wound repair was detected in EEF2K‐silenced melanoma cells." (PMID 35184394, 2022).
melanoma (continued). "Here, the importance of EEF2K in the proliferation of melanoma cells is demonstrated." (PMID 35408842, 2022). "Furthermore, the expression of PD-L1 was positively correlated with eEF2K level in tumor samples from patients with melanoma." (PMID 35347072, 2022). "Targeting EEF2K with NH125 reduced the phosphorylation of EEF2K protein in UACC 903 cells, suggesting that inhibiting its activity is causally associated with suppression of melanoma cell growth." (PMID 35408842, 2022). "EEF2K/p‐STAT3/SPP1 may be a novel oncogenic pathway in melanoma progression, which could be a target for novel combination therapy for melanoma." (PMID 35184394, 2022). "As a potential partner of eEF2K, we further analyzed whether eEF2K affects GSK3β phosphorylation in melanoma cells." (PMID 35347072, 2022). "We sought to verify whether EEF2K affects melanoma cell migration and invasion by utilising wound healing and transwell assays." (PMID 35184394, 2022). "We validated that EEF2K silencing could enhance the inhibitory effects of BET inhibitors on melanoma, probably by further downregulating SPP1 expression." (PMID 35184394, 2022). "Additionally, we screened the US FDA‐approved antitumour drugs library and identified cytarabine as a potential clinically applicable EEF2K inhibitor that has a synergistic effect with BET inhibitors on melanoma treatment." (PMID 35184394, 2022). "Our findings revealed that EEF2K/p‐STAT3/SPP1 might be a novel oncogenic pathway in melanoma progression and could serve as an important reference point for potential combination therapy for melanoma." (PMID 35184394, 2022). "Given that EEF2K positively regulates both SPP1 and p‐STAT3 and SPP1 is positively associated with p‐STAT3 in melanoma, we sought to verify whether EEF2K regulates SPP1 in a STAT3‐dependent manner." (PMID 35184394, 2022). "The role of EEF2K in cancer and melanoma remains both controversial and obscure." (PMID 35184394, 2022). "EEF2K mediates melanoma progression through p‐STAT3/SPP1 axis." (PMID 35184394, 2022). "The role of EEF2K has been reported in many types of tumours, but its role in melanoma remains unclear." (PMID 35184394, 2022). "All four siRNAs targeting EEF2K reduced proliferation of 1205 Lu melanoma cells (p < 0.0001)." (PMID 35408842, 2022). "Likewise, the number of invasive melanoma cells was also significantly decreased in EEF2K silencing and increased in EEF2K overexpression group." (PMID 35184394, 2022). "Moreover, we showed that disruption of EEF2K after BET inhibitor treatment largely attenuated the proliferation capacity of melanoma cells, which led to increased apoptosis and cell cycle arrest in the G0/G1 phase." (PMID 35184394, 2022). "We further screened the US FDA‐approved antitumour drug library and identified cytarabine as a potential clinically applicable EEF2K inhibitor that could synergise with BET inhibitors in melanoma treatment." (PMID 35184394, 2022). "Furthermore, BET inhibitor treatment combined with EEF2K silencing significantly suppressed melanoma cell proliferation." (PMID 35184394, 2022). "Genetic knockdown of EEF2K significantly melanoma cell growth in culture and as tumours in animals in a manner similar to that observed following the knockdown of V600EBRAF protein, which suggested the potentially important role of translational elongation in the survival of melanoma cells." (PMID 35408842, 2022). "Furthermore, eEF2K inhibitor, NH125 treatment or eEF2K knockdown enhanced the efficacy of PD-1 mAb therapy in a melanoma mouse model." (PMID 35347072, 2022). "To explore whether STAT3 contributes to EEF2K‐mediated melanoma progression, we further evaluated the effect of EEF2K on melanoma cells in the presence of stattic." (PMID 35184394, 2022). "In contrast, EEF2K overexpression promoted melanoma cell proliferation, migration and invasion." (PMID 35184394, 2022).
melanoma (continued). "Based on these results, we speculated that SPP1 functions as an effector of EEF2K in the context of melanoma progression." (PMID 35184394, 2022). "Additionally, EEF2K protein amounts were reduced to undetectable levels in melanoma cell lines transfected with 200 pmole of EEF2K-targeted siRNA #1." (PMID 35408842, 2022). "In this study, we found that EEF2K might play a role in the regulation of melanoma progression through the p‐STAT3/SPP1 pathway." (PMID 35184394, 2022). "IHC staining revealed that EEF2K was differentially expressed in melanoma." (PMID 35184394, 2022). "By assessing the clinical significance of the eEF2K-PD-L1 pathway in PD-1 blockade-treated patients with melanoma, we found that high eEF2K expression could predict a better therapeutic outcome and longer OS time, suggesting eEF2K may be a potential biomarker for the efficacy of PD-1 mAb therapy." (PMID 35347072, 2022). "Doxorubicin treatment could induce eEF-2K activation and autophagy in melanoma cells." (PMID 31616642, 2019). "eEF2K is activated by β2-AR/PKA signaling in cardiomyocytes and melanoma cells and by the inhibition of mTORC1/p70S6K cascade, the latter also responsive to β2-AR/Gαs/adenylyl cyclase/PKA signaling." (PMID 35256673, 2022). "Results showed that EEF2K silencing increased the percentage of apoptotic cells and cell arrest in the G0/G1 phase in both SK‐MEL‐28 and A375 melanoma cells, and decreased the cell percentage in S and G2/M phases." (PMID 35184394, 2022). "We used a PD-1 mAb and NH125, an eEF2K inhibitor, to treat immune-competent mice inoculated with B16F10 melanoma cells." (PMID 35347072, 2022). "We also determined the effects of eEF2K on tumor growth and cytotoxicity of CD8+ T cells in TIME in a mouse melanoma model." (PMID 35347072, 2022). "Intriguingly, EEF2K silencing combined with BET inhibitor treatment further inhibited cell proliferation and promoted apoptosis in melanoma." (PMID 35184394, 2022). "Transfection‐induced re‐expression of SPP1 partly negated the inhibitory effect of EEF2K silencing on melanoma, whereas inhibition of SPP1 or STAT3 significantly abolished the efficacy of EEF2K on melanoma cells." (PMID 35184394, 2022). "Cytarabine, a potential clinically applicable EEF2K inhibitor, synergises with BET inhibitors in melanoma treatment." (PMID 35184394, 2022). "Knockdown of eEF2K decreased PD-L1 expression and enhanced CD8+ T cell activity, thus dramatically attenuating murine B16F10 melanoma growth in vivo." (PMID 35347072, 2022). "In melanomas, the administration of doxorubicin can trigger caspase-3-driven pyroptosis via GSDME, and the antitumor efficacy is enhanced when the elongation factor-2 kinase (eEF-2K) is inhibited." (PMID 38304430, 2024). "In some cases, eEF2K may upregulate the levels of STAT3, as observed in various cell types, including melanoma." (PMID 37875468, 2023). "The absence of eEF-2K results in the inhibition of autophagy and enhancement of pyroptosis, which contributes to the modification of the sensitivity of melanoma cells to DOX." (PMID 36831326, 2023). "Considering that the role of EEF2K in melanoma has never been elucidated, it is imperative to clarify the regulatory function of EEF2K in melanoma progression." (PMID 35184394, 2022). "The compound NH125, which not only is an EEF2K inhibitor but can promote EEF2 phosphorylation to regulate protein translation, demonstrated a similar pattern of inhibiting both cholesterol metabolism and proliferation of melanoma cells." (PMID 35408842, 2022). "The reduction in cellular proliferation when targeting EEF2K was similar to that observed when the BRAF (positive control) was knocked down, suggesting that EEF2K might be an important target in melanoma." (PMID 35408842, 2022). "Off-target effects were ruled out by coculturing WT and eEF-2K+/+ CD8+ OT-I T cells with control B16 (OVAnull) melanoma cell lines." (PMID 35108044, 2022).
melanoma (continued). "We further showed that eEF2K promotes stabilization of PD-L1 protein through its interaction with GSK3β, and that knockdown of eEF2K decreased PD-L1 expression and increased CD8+ T cell number and granzyme B (GZMB) in tumor tissues in a mouse melanoma model." (PMID 35347072, 2022). "Mechanistically, we demonstrated that EEF2K upregulates the phosphorylation of STAT3 (p‐STAT3) at Tyr705, which binds to the promoter region of SPP1 and enhances its transcription, thus facilitating melanoma progression." (PMID 35184394, 2022). "The A484954 EEF2K inhibitor did not reduce the levels of pEEF2K or inhibit proliferation of melanoma cells even at 100 μM concentrations and was therefore not further evaluated in this study." (PMID 35408842, 2022). "Here, we identified that EEF2K/p‐STAT3/SPP1 may be a novel oncogenic pathway in melanoma progression and could be a potential target for a novel combinational therapy for melanoma." (PMID 35184394, 2022). "However, eEF-2K silencing shifted the doxorubicin-induced autophagy into GSDME-modulated pyroptotic cell death, thus increasing the sensitivity of melanoma cells to doxorubicin." (PMID 31616642, 2019). "Moreover, co‐immunoprecipitation assay demonstrated that endogenous EEF2K was precipitated with endogenous STAT3, but not with PKM2, suggesting that EEF2K promotes the phosphorylation of STAT3 in a PKM2‐independent manner in melanoma cells." (PMID 35184394, 2022). "However, comparable PKM2 expression in control versus EEF2K silencing cells and lack of interaction between EEF2K and PKM2 suggested that EEF2K increases the level of p‐STAT3 in a PKM2‐independent manner in melanoma." (PMID 35184394, 2022).